Y_RNA (Y RNA )
Gene: Miscellaneous RNA gene on chromosome 18 (23,456,371 to 23,456,467, forward strand). Ensembl gene ENSG00000199357.
Homologues: Orthologues: chimpanzee Y_RNA (100% identical), macaque Y_RNA (96% identical). Paralogues in human: RNY4 (90% identical), RNY4P3 (89% identical), RNY4P7 (89% identical), Y_RNA (89% identical), RNY4P10 (88% identical), RNY4P6 (88% identical), Y_RNA (88% identical), RNY4P13 (87% identical), RNY4P14 (87% identical), RNY4P25 (87% identical), Y_RNA (87% identical), RNY4P23 (86% identical), and 92 more.